HGF (hepatocyte growth factor)
Diseases named in the same sentence as HGF in open-access papers (continued):
Sharing a sentence is not in itself a finding about the gene and the disease.
prostate tumor (7 papers, 2014 to 2025). "Transgenic overexpression of Met in mouse prostate epithelial cells is sufficient to induce PIN under HGF conditions and markedly promotes prostate tumor initiation, invasion and metastasis in a Pten-deficient background." (PMID 37668356, 2023). "Furthermore, alterations in HGF, observed in 1.5% of our cohort, were significantly associated with greater telomeric content in kidney, brain, and prostate tumors." (PMID 35227290, 2022). "Previous studies indicated that HGF significantly increases the proliferation and invasion of prostate tumor cells." (PMID 33540941, 2021). "HGF alterations were classified as amplifications in 95.7% of kidney, brain, and prostate tumors." (PMID 35227290, 2022).
skin cancer (7 papers, 2011 to 2024). "In summary, we have identified the HGF/MET pathway as critical to skin tumor growth and malignant conversion in Tpl2−/− mice." (PMID 30631034, 2019). "We examined the role of LKB1 in suppression of UVB-induced skin cancer using the HGF transgenic mouse model by generating the HgfTg; Lkb1+/− mouse." (PMID 25329316, 2014). "Reduced amounts of LKB1 are enough to impair UVB-induced DNA repair and cooperate with HGF signaling to promote skin cancer." (PMID 25329316, 2014). "Xenografts of cancer cells together with XP-C fibroblasts in the absence or the presence of HGF inhibitors may be expected to be a novel therapeutical approach for XP-C patients suffering from aggressive skin cancers (SCCs)." (PMID 39409898, 2024). "Newborn litters (post-natal day 4) from the parental strains and the HGF+ × [m1m2]+/− hybrid were exposed to UVR and monitored for development and growth of skin tumors." (PMID 22699362, 2013). "Consistent with prior reports, UVR treatment elicited pigmented skin tumors in the majority (68 %) of HGF+ mice, with no mice displaying more than one tumor." (PMID 22699362, 2013). "In the absence of UVR, no skin tumors were observed in either the HGF+ or the HGF+ [m1m2]+/− hybrid groups, indicating the observed tumors were initiated by UVR treatment." (PMID 22699362, 2013).
ulcerative colitis (7 papers, 2010 to 2023). An inflammatory bowel disease involving the mucosal surface of the large intestine and rectum. "Hepatocyte Growth Factor (HGF) was markedly down-regulated in all the diseased tissues (ulcerative colitis, adenoma or adenocarcinoma) studied." (PMID 21059221, 2010). "This tendency to the higher TGF-β1 and HGF plasma levels in the IBD patients is consistent with the current view that both cytokines exert aggressive effects on pathophysiology events of ulcerative colitis and that TGF-β might be the major cytokine during times of active inflammation." (PMID 32377513, 2020).
colorectal tumor (6 papers, 2017 to 2025). "Secretion of hepatocyte growth factor by myofibroblasts inducing nuclear translocation of β-catenin activates Wnt signaling, thereby generating stem-like features in more differentiated colorectal tumor cells." (PMID 40361430, 2025). "In fact, MET activation in colorectal tumors occurs primarily via paracrine HGF stimulation by the surrounding stroma." (PMID 28445144, 2017). "To uncover it, we compared the efficacy of AIs in wild-type and human HGF knock-in SCID mice bearing orthotopic human colorectal tumors." (PMID 28445144, 2017).
Fulminant hepatic failure (6 papers, 2010 to 2022). Hepatic failure refers to the inability of the liver to perform its normal synthetic and metabolic functions, which can result in coagulopathy and alteration in the mental status of a previously healthy individual. "Hepatocyte growth factor (HGF) was first purified and isolated as a potent hepatocyte mitogen from the plasma of patients with fulminant hepatic failure." (PMID 34448078, 2021). "Hepatocyte Growth Factor (HGF) from blood plasma of patients with fulminant hepatic failure has been discovered to be a factor that strongly stimulates DNA synthesis in hepatocytes." (PMID 32983173, 2020). "HGF has been isolated and purified from the plasma of patients with fulminant hepatic failure and from rat platelets." (PMID 21603218, 2011).
Hyperglycemia (6 papers, 2012 to 2024). An increased concentration of glucose in the blood. "In β-cells Met−/− mice, a mild hyperglycemia and loss of acute-phase insulin response to glucose highlight the importance of HGF-Met signaling for normal glucose-dependent insulin secretion and homeostasis." (PMID 38654922, 2024). "Moreover, hyperglycemia and metformin resulted in an increase of the mRNA levels of HGF (1.7-fold, p = 0.001), and IL-6 (2.8-fold, p = 0.01) although this increase remained below normal level observed at euglycemia." (PMID 26861446, 2016). "Glucose levels remained similar in diabetic-treated and non-treated groups, suggesting that neither HGF nor G-CSF treatments have any effect on hyperglycaemia." (PMID 22460762, 2012).
lung diseases (6 papers, 2015 to 2025). "Previous studies attributed the reparative and immunomodulatory roles of MSCs in spinal cord injury models and lung diseases to the actions of secreted HGF." (PMID 35740995, 2022). "Hepatocyte growth factor was involved in the pathogenesis of various lung diseases as it was significantly higher in COPD patients compared to control patients." (PMID 34481483, 2021). "Novel therapeutic strategies using HGF to fight lung diseases have been suggested because HGF exhibited sustained barrier-protective effects on ECs." (PMID 25888925, 2015). "Supportive of a potential application of HGF in the CF setting, several in vivo studies indicated that HGF administration can mitigate the effects of acute and chronic lung injuries, having beneficial effects both at the initial and late stages of lung disease." (PMID 35004859, 2021). "These donor-recipient signaling networks, impossible in native lung diseases, define CLAD as a disease of cellular miscommunication with specific therapeutic targets (HGF-MET, TRAIL, PD-L1/PD-1) for interrupting progression." (PMID 41122970, 2025).
ovarian tumors (6 papers, 2015 to 2025). "Activation of the HGF/c-MET axis has been demonstrated in certain ovarian tumours, and been found to be associated with decreased overall survival, suggesting its potential as a therapeutic target." (PMID 26138303, 2015). "Firstly, HGF‐dependent cMET activation in ovarian tumors could be exerted by an autocrine loop, by which HGF is expressed and excreted by the tumor cells themselves." (PMID 33738970, 2021). "Moreover, an elevated HGF expression is detectable in epithelial cell components of ovarian tumors and in MSC suggesting an autocrine and/or paracrine stimulation of ovarian tumor growth including tumor cell protection." (PMID 28212658, 2017).
papillary thyroid cancer (6 papers, 2014 to 2021). "In addition, HGF stimulation of papillary carcinoma of the thyroid (PTC) cells causes up-regulation of COX-2 and down-regulation of CD82/KAI-1; both these molecules have a major role in controlling tumor cell invasiveness." (PMID 28548071, 2014). "Studies have shown that LAMB3 leads to tumor invasion via Akt activation induced by the HGF/c-MET axis in papillary thyroid cancer." (PMID 31485443, 2019). "In fact, Met protein-positive papillary carcinoma cells are highly responsive to hepatocyte growth factor (HGF), which is effective in stimulating tumor cell adhesion, migration and invasiveness." (PMID 28548071, 2014). "In fact, Met protein-positive papillary carcinoma cells are highly responsive to hepatocyte growth factor (HGF) which is effective in stimulating tumor cell adhesion, migration, invasiveness and induces the synthesis and release of chemokines and growth factors." (PMID 28548071, 2014). "It was found that papillary carcinoma cells were active in releasing chemotactic activity, that HGF or interleukin (IL)-1β induced a four-fold increase in the amount of chemotactic activity released, and that normal thyroid cells obtained from the same patients were as effective as tumor cells." (PMID 28548071, 2014). "Thus, HGF-stimulated papillary carcinoma cells might take advantage of a favorable ECM microenvironment, rich in oncofetal FN and poor in VN, to display their marked invasive behavior." (PMID 28548071, 2014). "HGF or agonistic monoclonal antibodies against Met protein stimulate the migratory capacity of PTC cells; in fact, they act as chemoattractants for tumor cells in an in vitro invasion assay and induce migration of papillary carcinoma cells through nucleopore filters coated with matrigel." (PMID 28548071, 2014).
Peritoneal Fibrosis (6 papers, 2014 to 2024). Disorder characterized by a wide range of structural changes in PERITONEUM, resulting from fibrogenic or inflammatory processes. "In another study, macrophages were employed as vehicles to intravenously express and deliver the HGF gene to mice with peritoneal fibrosis induced by chlorhexidine gluconate." (PMID 39749340, 2024). "HGF secreted by injected mesenchymal stem cells (MSCs) ameliorated chlorhexidine digluconate (CG)-induced peritoneal fibrosis." (PMID 33477422, 2021). "HGF has been reported to be involved in preventing fibrosis in several organ tissues, and HGF had been demonstrated to ameliorate peritoneal fibrosis in an animal model." (PMID 32296091, 2020). "HGF elicits the regression of peritoneal fibrosis, in which TGF-β-induced myofibroblasts are critical for tissue scarring." (PMID 30692872, 2018). "Since HGF ameliorated peritoneal fibrosis in an ex-vivo study, a clinical study as ours looks opportune." (PMID 25519900, 2014). "We investigated whether HGF, an anti-fibrotic factor, can prevent the progression of peritoneal fibrosis by using macrophages to establish an efficient HGF gene delivery." (PMID 37108115, 2023). "In conclusion, our results indicate that HGF gene transfer by macrophages using CGMs is a novel gene therapy that may have potential for the treatment of peritoneal fibrosis." (PMID 37108115, 2023). "Thus, we attempted to treat peritoneal fibrosis by sonoporation-based human HGF (hHGF) gene transfection in mice." (PMID 33477422, 2021). "Our result, nevertheless, suggested that HGF may have a role in the modulation of peritoneal fibrosis following peritonitis." (PMID 32296091, 2020). "Thus, we hypothesized that HGF may be a target for peritoneal fibrosis treatment." (PMID 37108115, 2023). "Hepatocyte growth factor (HGF) counteracts peritoneal fibrosis in animal models and in-vitro studies, but no study explored effluent HGF in peritoneal dialysis (PD) patients with ultrafiltration failure (UFF)." (PMID 25519900, 2014).
renal failure (6 papers, 2014 to 2025). "Moreover, the epithelial interactions were less active in the COVID + kidney failure group, especially inflammation-related signals, such as HGF, ICAM, WNT, CD226, and NECTIN, indicating a weakened immune response." (PMID 39202702, 2024).
spinal cord injury (6 papers, 2011 to 2023). Penetrating and non-penetrating injuries to the spinal cord resulting from traumatic external forces (e.g., WOUNDS, GUNSHOT; WHIPLASH INJURIES; etc.). "This study evaluates the impact of a dual therapeutic intervention utilizing hepatocyte growth factor (HGF) and hiPSC-NS/PC transplantation on motor function restoration following spinal cord injury (SCI)." (PMID 37845736, 2023).
systemic sclerosis (6 papers, 2012 to 2023). A chronic disorder, possibly autoimmune, marked by excessive production of collagen which results in hardening and thickening of body tissues. "SNP Rs3735520 was found to associate with end-stage lung disease in Japanese systemic sclerosis patients, and carriers of the HGF promoter with the HGF −1652 TT allele had a relative inability to increase circulating HGF levels." (PMID 24716444, 2014). "Recombinant HGF selectively abolishes connective tissue growth factor (CTGF) expression and collagen accumulation, effects mediated through cMET phosphorylation in lung fibroblasts isolated from Caucasian but not from AA patients with systemic sclerosis (SSc)." (PMID 37046676, 2023).
alcoholic hepatitis (5 papers, 2015 to 2024). Acute hepatitis resulting from ingestion of alcohol. "Additionally, activin stimulates apoptosis of hepatocytes, and increased levels of circulating activin are observed in severe alcoholic hepatitis patients, suggesting that activin exerts direct effects on liver function, likely altering HGF production." (PMID 38654064, 2024). "It is probable because HGF exerts biological activities in regulating lipid metabolism, as well as in stimulating hepatocyte proliferation through the c-Met/HGF receptor, as was previously demonstrated in acute alcoholic hepatitis." (PMID 36359733, 2022).
alcoholic liver diseases (5 papers, 2015 to 2025). A disorder caused by damage to the liver parenchyma due to alcohol consumption. "This study highlights the therapeutic potential of recombinant Tarim red deer HGF in the treatment of alcoholic liver disease, paving the way for future research and clinical applications." (PMID 40723349, 2025). "The recombinant Tarim red deer HGF protein obtained was utilized for treatment, and its therapeutic effects on mouse alcoholic liver disease were evaluated by measuring liver histology, blood biochemical indicators, and liver biochemical markers." (PMID 40723349, 2025). "This study explores the potential of a recombinant Tarim red deer hepatocyte growth factor (HGF) protein as a regenerative therapy for alcoholic liver disease." (PMID 40723349, 2025). "This study investigates the recombinant Tarim red deer hepatocyte growth factor (HGF) in a mouse model to develop an HGF/c-Met-based regenerative therapy for alcoholic liver disease." (PMID 40723349, 2025). "In conclusion, our study demonstrates that recombinant Tarim red deer HGF effectively reduces liver damage in a mouse model of alcoholic liver disease." (PMID 40723349, 2025). "The research involved the construction of a fusion protein derived from the HGF of Tarim red deer and the assessment of its effects in a mouse model of alcoholic liver disease." (PMID 40723349, 2025). "There are only few reports on HGF in patients with alcoholic liver disease and the majority of them were based on small groups of patients." (PMID 26448742, 2015). "Our study demonstrated that recombinant HGF derived from Tarim red deer significantly enhanced the liver’s antioxidant capacity, improved lipid deposition in the liver, and promoted hepatocyte regeneration, thereby effectively reducing liver damage in a mouse model of alcoholic liver disease." (PMID 40723349, 2025). "PGE2 or HGF by SkMSCs might decrease ethanol-induced hepatic injury by suppressing inflammatory M1 macrophages or promoting anti-inflammatory M2 macrophages; this is because alcoholic liver diseases are exacerbated by inflammatory neutrophils and macrophages." (PMID 35165521, 2022). "To assess the therapeutic efficacy of the recombinant Tarim red deer HGF/SF Receptor (MET) agonist produced via this method, we established a mouse model of alcoholic liver disease characterized by chronic alcohol feeding followed by acute alcohol gavage, referred to as the NIAAA or Gao-Binge model." (PMID 40723349, 2025).
Autoimmunity (5 papers, 2013 to 2024). The occurrence of an immune reaction against the organism's own cells or tissues. "HGF is a growth factor capable of preventing autoimmunity progression by regulating pathophysiological processes such as immune cell migration, antigen presentation, and cytokine production." (PMID 38312681, 2024). "This and a number of further activities of HGF/Met signaling on other immune cells suggest the HGF/Met pathway as a potential target for treatment of inflammatory and autoimmune disorders, including skin diseases and transplantation." (PMID 29616031, 2018). "Other studies suggest a protective role of HGF/Met signaling against autoimmunity by directing DCs toward a tolerogenic phenotype." (PMID 29616031, 2018). "Complementary to its impact on CD4+ T-cell CNS autoimmunity, our findings further suggest that HGF treatment could be exploited to control CD8+ T-cell-mediated, MHC I-restricted autoimmune dysfunctions such as MS." (PMID 24344806, 2013). "Complementary to its impact on CD4+ T-cell CNS autoimmunity and myelin repair, our findings further suggest that HGF treatment could be exploited to control CD8+ T-cell-mediated, MHC I-restricted autoimmune dysfunctions such as MS." (PMID 24344806, 2013).
bacterial pneumonia (5 papers, 2011 to 2025). Acute infection of the lung parenchyma caused by bacteria (e.g., Streptococcus pneumoniae, Haemophilus influenzae, Chlamydia pneumoniae, Mycoplasma pneumoniae, and Legionella pneumophila). "For instance, Aφs that phagocytose apoptotic neutrophils produce hepatocyte growth factor (HGF) during bacterial pneumonia in mice." (PMID 30108592, 2018). "Several studies have convincingly demonstrated that plasma/serum HGF levels become elevated in bacterial pneumonia." (PMID 21429184, 2011). "Serum HGF levels were higher in patients with Legionella pneumonia than in those with other bacterial pneumonia, pulmonary tuberculosis, and controls." (PMID 21429184, 2011). "Further, the serum HGF levels were significantly higher in Legionella pneumonia cases than those in other bacterial pneumonia cases." (PMID 21429184, 2011). "Serum HGF levels were significantly elevated in Legionella pneumonia cases, other bacterial pneumonia cases, and pulmonary tuberculosis cases as compared to those in normal subjects." (PMID 21429184, 2011). "In summary, the present work provides evidence that Dppi-activated leukocyte proteases regulate levels of HGF, while suggesting that this effect may be offset in the context of bacterial pneumonia by influx of HGF from the blood." (PMID 25938594, 2015). "HGF levels in non-suvivors of other bacterial pneumonia (2 cases) were 5,183 pg/mL and 4,257 pg/mL." (PMID 21429184, 2011).